TLR3 (toll like receptor 3)
Diseases named in the same sentence as TLR3 in open-access papers (continued):
Sharing a sentence is not in itself a finding about the gene and the disease.
melanoma (continued). "We have characterized a TLR3-dependent pathway of apoptosis induction in melanoma cells that requires the adapter TRIF and uses similar signalling to TNF-R1, involving the activation of caspase-8 controlled by cIAP1/2." (PMID 35044632, 2022). "To modify cell surfaces with PAMPs, we first used Aza to stimulate B16-F10 melanoma cells to express TLR3 on their cell surface." (PMID 35805071, 2022). "Here we treat B16F10 melanoma with agonists of the endosomal TLRs TLR3, TLR7 and TLR9 to understand the influence of these agents on immune polarization in a ‘cold’ tumor model." (PMID 34381732, 2021). "It has been reported that TLR3 stimulation in a mouse model of melanoma repressed the progression of tumour through myeloid DC‐mediated activation of NK cells." (PMID 33336901, 2021). "Using single-cell RNA-sequencing, we address this by comparing the tumor immune composition of B16F10 melanoma following treatment with agonists of TLR3, TLR7, and TLR9." (PMID 34381732, 2021). "Subcutaneous B16F10 melanoma tumors were grown to 150 mm3 then injected I.T. with selective agonists targeting TLR3, TLR7or TLR9, or vehicle control respectively." (PMID 34381732, 2021). "TLR3 is highly expressed on human melanoma cells, and TLR3 activation can induce activation of downstream NF-κB and cell migration." (PMID 33986756, 2021). "Encouraging results were obtained in mice tumor models of melanoma, breast cancer and others, with TLR3, TLR7, TLR8 and TLR9 ligands." (PMID 32708142, 2020). "Although several studies advanced the potential of TLR3 as a therapeutic target for hepatoma, melanoma, and clear cell renal carcinoma, the mechanisms mediating its antitumor effects remain insufficiently characterized." (PMID 33173017, 2020). "Poly-I:C stimulation of TLR3 efficiently repolarized TAMs in melanoma and now is under evaluation as a cancer vaccine to improve the antitumor immune response in advanced cancers." (PMID 32708142, 2020). "PolyI:C, a TLR3 agonist, which activates immune cells to fight cancer progression, was deemed a potent adjuvant for treating melanoma, metastatic lung and cervical cancer." (PMID 28427199, 2017). "Previous studies in our laboratory demonstrated that C10 decreased high constitutive TLR3 and Wnt5a expression in human malignant melanoma, papillary thyroid, and pancreatic cancer cell lines." (PMID 29371911, 2017). "To determine if Poly(I:C) uses innate immunity to inhibit melanoma metastasis, we evaluated the roles of the Toll-like receptor 3 (TLR3) and RIG-helicase (RLH) innate immune pathways." (PMID 27198666, 2016). "We also demonstrated that human DCs coincubated with H-1PV-induced melanoma TCLs showed enhanced expression of TLR3, TLR9, and other maturation markers." (PMID 24822170, 2014). "TLR3 agonists have been shown to be well-tolerated and effective in both directly killing cancer cells and directing immune responses in melanoma." (PMID 24744758, 2014). "This is in contrast with what has been found by others, e.g., co-administration of IMQ and anti-CD40 is ineffective against intradermal B16 melanomas, and required a combination of TLR3, TLR4 and TLR7 stimulation to produce 50% tumor rejection." (PMID 25518732, 2014). "Taken together, these results suggest that IL-27 enhances the expression of TRAIL and TLR3 in human melanomas and inhibits their tumor growth in cooperation with poly(I:C), partly in a TRAIL-dependent manner." (PMID 24155891, 2013). "We here show that IL-27 enhances the expression of TNF-related apoptosis inducing ligand (TRAIL) and TLR3 in human melanomas and therefore inhibits their tumor growth in cooperation with poly(I:C) partly in a TRAIL-dependent manner." (PMID 24155891, 2013). "In virtue of their TLR expression, B16 melanoma cells were found to respond to ligands to TLR3 and TLR4 by releasing substantial levels of IFN-I that induced DC activation and resulted in tumor growth inhibition by the host." (PMID 24400008, 2013).
melanoma (continued). "For example TLR7/8 agonists were shown to increase tumor viability and metastasis in lung cancer cells and TLR3 agonists shows proliferation of human melanoma cells." (PMID 23151919, 2012). "The observation quickly gained support from other studies that confirm a role for TLR3 in the tumorigenesis of hepatoma, melanoma and clear cell renal carcinoma." (PMID 21861882, 2011). "Using a panel of various human carcinoma and melanoma cell lines, we decided to address the following questions: 1) What is the influence of a TLR3 synthetic ligand on the status of the IAP proteins?" (PMID 20576118, 2010). "This pathway has been harnessed in preclinical studies showing that co-cultures with the TLR3 agonist Poly I: C can directly induce apoptosis in various cancer cell types, including breast, cervical, melanoma, colorectal, hepatocellular carcinoma, oral squamous cell carcinoma, and lung cancer." (PMID 39988665, 2025). "Transcriptomic data support this observation because actinomycin D and nutlin-3a acting alone and in combination up-regulate TLR3 expression in the A549 cell line, and A+N up-regulates TLR3 expression in melanoma (A375), osteosarcoma (U-2 OS), and another lung cancer (NCI-H460) cell line." (PMID 40362653, 2025). "We used this melanoma cell model to test whether expression of Usp27x can also control apoptosis-induction through TLR3." (PMID 35044632, 2022). "In melanoma, TLR3 agonists could induce antitumor immunity by activating NK cells to hinder B16 melanoma lung metastasis, whereas the activation of NK cells in lung was mediated by alveolar macrophages and shapes macrophage behavior." (PMID 35413927, 2022). "Moreover, the interaction of TLR2, TLR3 and TLR4 with their ligands on human melanoma cells was associated with increased cell migration and tumour metastasis." (PMID 33336901, 2021). "Overcoming the resistance via cIAPs suppression probably depends on cancer types or cancer natural history because resistant melanoma cell lines or nasopharyngeal carcinoma latently infected by the Epstein-Barr virus can be sensitized to TLR3-induced apoptosis by the use of smac mimetics." (PMID 30158588, 2018). "Similar findings were shown in Me 260 cells, which failed to respond to poly(I:C) alone, but IFN-α+ poly(I:C) could induce up-regulation of TLR3 and induced melanoma cell death." (PMID 26208481, 2015). "To determine in vivo whether EBERs could promote tumor growth through TLR3 signaling pathways, we used TLR3 knockout mice (TLR3−/−) to verify the impact of EBERs on growth of syngeneic tumor (B16, mouse melanoma cells)." (PMID 26172457, 2015). "Moreover, a series of studies confirm the potential of TLR3 as therapeutic target for hepatoma, melanoma and clear cell renal carcinoma." (PMID 21861882, 2011). "The TLR3‐agonist poly(I:C) has been developed to simulate pathogen infection and promote immune system activation to enhance anticancer therapy and has shown significant therapeutic effects in preclinical models of melanoma, kidney cancer, and colorectal cancer." (PMID 37283287, 2023). "In addition, the melanoma mouse model demonstrated that mobilization of cDC1 alone is insufficient in generating anti-tumor T cell response in tumors and that addition of the TLR3 agonist, which activates type I IFN signaling in cDC1, is necessary to enhance response to anti-PD-1 Ab." (PMID 35432377, 2022). "The cooperative effect could be ascribed to the augmented expression of TLR3, but not retinoic acid-inducible gene-I or anti-melanoma differentiation-associated gene 5, by IL-27." (PMID 24155891, 2013). "By flow cytometry, we analyzed the expression of proteins, including TLR3, TRAF6, and SNCA, as a marker of macrophages that have taken up Fibroblast-derived, keratinocyte-derived, and melanoma-derived melanosomes, respectively (workflow)." (PMID 38719996, 2024). "TLR3/4 can induce apoptosis in macrophages, while TLR3 is more widely expressed than TLR4 and can kill for instance melanoma cells." (PMID 36131076, 2023).
melanoma (continued). "The treatment of the miR-148i vaccine made of miR-148i, poly I:C, and ovalbumin encapsulated into polypeptide micelles significantly enhances Toll-like receptor 3 (TLR3)-induced dendritic cell maturation and activation in mice bearing melanoma tumors." (PMID 37345170, 2023). "More specifically, the ablation of this demethylase in B16 melanoma triggers ERV transcription, which is sensed by the PRRs TLR3 and MDA5 (the latter being enconced by the Ifih1 gene), consequently eliciting type-I IFNs." (PMID 35681511, 2022). "In melanoma patients, peripheral cDC1s have a defective ability to upregulate CD83 after TLR3/7/8 agonists stimulation ex vivo." (PMID 36230990, 2022). "Melanoma cell-derived sEVs were shown to induce lung PMN formation by delivering small nucleic RNAs, which activate toll-like receptor 3 in lung epithelial cells." (PMID 34646366, 2021). "Necroptosis has been reported to enhance anti-tumor immunity in colon cancer and melanoma and RIPK3 expression status is proposed to influence the clinical outcome of TLR3-based cancer immunotherapy." (PMID 33036630, 2020). "Similar to our findings, stimulation of TLR3 by Poly(I:C) induced migration and invasion in HNSCC, melanoma and lung cancer." (PMID 33036630, 2020). "Biopsies of the VSME were obtained from participants on two clinical trials who were immunized with multiple melanoma peptides (MELITAC 12.1) in adjuvants comprising IFA and/or the TLR3-agonist pICLC." (PMID 32350119, 2020). "TLR3, which is aberrantly expressed in hepatocellular carcinoma (HCC), breast, melanoma, and metastatic lung carcinoma, was recently reported to trigger apoptosis in these cancers, when induced." (PMID 28427199, 2017). "The complementary roles of TLR3 and MDA5 have also been demonstrated in other studies with melanoma and NK cells." (PMID 26208481, 2015). "Distribution of the most common haplotypes within TLR2, TLR3 and TLR4 in German melanoma patients and German controls." (PMID 21931695, 2011). "They used phenylmethimazole, an inhibitor targeting TLR-3, to decrease TLR-3 activity, expression and downstream signaling of Wnt5A both in vitro and in vivo, providing further evidence that targeting pathways that control Wnt5A may be useful for inhibiting melanoma progression." (PMID 24281103, 2010). "This suggests that R.E may induce IFN production througha receptor other than TLR3, potentially via MDA5, which is highlyexpressed in melanoma cells." (PMID 41341044, 2025). "Their vaccine consisted of six non-mutated melanoma-specific helper peptides (6MHP) and an additional BRAF-V600E peptide combined with two agents that enhance APC function and activation, toll-like receptor 3 (TLR3) agonist and CD40 agonist." (PMID 39682188, 2024). "Ongoing trials investigate the application of TLR3 agonists in other malignancies, among others, in advanced colorectal cancer in combination with pembrolizumab (NCT04119830), in malignant melanoma (NCT04093323) and in the neoadjuvant setting in malignant pleural mesothelioma (NCT04345705)." (PMID 34025657, 2021). "Furthermore, Flt3L injection combined with polyinosinic:polycytidylic acid (polyIC), a TLR3 agonist, induced the expansion and activation of CD103+ DC progenitors (cDC1) in a murine melanoma model, leading to an increased sensitivity to checkpoint blockade." (PMID 34025657, 2021). "TLR3 targeting ligands and STING agonists are currently being tested in clinical trials as adjuvant therapy, or along with other drugs and vaccines, against a variety of cancers such as melanoma, bladder cancer, and lymphomas." (PMID 32486450, 2020). "Furthermore, IL-27 has the potential to interact with novel therapeutics; it synergizes with poly(I:C), a TLR3 agonist, to reduce proliferation of melanoma and prostate cancer cells via TRAIL or TLR3, respectively." (PMID 31681561, 2019).
melanoma (continued). "IPH-3102 is another specific TLR3 agonist with high molecular mass that mimics dsRNA, activates NF-κB and induces type I IFN responses in vitro, thereby exerting cytotoxic effects against melanoma and carcinoma cells." (PMID 23151919, 2012). "Furthermore, we established a subcutaneous B16-F10 melanoma model for intratumoral BCG treatment and compared wild type mice to TLR2-/-, TLR3-/-, TLR4-/-, TLR7-/-, TLR3/7/9-/-, caspase 1-/-, caspase 11-/-, IL-1R-/-, cGAS-/-, STING-/-, IFNAR-/-, MyD88-/-deficient animals." (PMID 38835781, 2024). "In a cohort of 54 melanoma patients receiving anti-PD-1 antibody monotherapy, non-responding patients had abundant expressions of immune gene markers such as TNFAIP3 (encoding A20) and TLR3 in tumors, which was associated with a dampened immune response." (PMID 37175874, 2023). "However, our concept is unique, because of the specific combination of TLR ligands (particularly TLR2, TLR3, and TLR7/8), which seems to have an extraordinary effect on innate immunity activation and tumor elimination, as previously presented in melanoma and pancreatic adenocarcinoma mouse models." (PMID 31083581, 2019). "have previously shown that non-malignant epithelial cells are less sensitive than melanoma cells to poly I:C-induced apoptosis and our data support the hypothesis that TLR3-mediated apoptosis is selective for cancer cells also in the prostate 32,35." (PMID 25444175, 2015). "Using the TLR3 and STING agonists poly(I:C) and cGAMP, respectively, the expression of the MA signature was induced in murine BMDM, but not in B16F10 melanoma cells." (PMID 32486450, 2020). "Finally, we did not observe TLR3, TLR7 or TLR9 expression in previously published RNA-Seq data of in vitro cultured B16F10 melanoma (data not shown), ruling our direct effects of agonist treatment on the tumor itself." (PMID 34381732, 2021). "Thus, Poly(I:C) inhibits melanoma metastasis, Chi3l1/BRP-39 accumulation and IL-13Rα2 expression via the RLH innate immune pathway and TLR3 does not play a major role in these responses." (PMID 27198666, 2016).
influenza (83 papers, 2007 to 2025). An acute viral infection of the respiratory tract, occurring in isolated cases, in epidemics, or in pandemics; it is caused by serologically different strains of viruses (influenzaviruses) designated A, B, and C, has a 3-day incubation period, and usually lasts for 3 to 10 days. "In humans, a missense mutation F303S in the TLR3 gene was shown to be associated with influenza-associated encephalopathy, a neurological symptom of severe influenza." (PMID 38892096, 2024). "We replicated the enrichment in rare predicted LOF (pLOF) variants at 13 influenza susceptibility loci involved in TLR3-dependent type I IFN immunity (OR = 3.70[95%CI 1.3–8.2], P = 2.1 × 10−4)." (PMID 37020259, 2023). "By contrast, inborn errors of the TLR3 pathway underlie critical influenza or COVID-19 pneumonia by impairing the production of type I IFNs by cells other than pDCs, such as pulmonary epithelial cells." (PMID 34413140, 2021). "In fact, mice deficient in TLR3 had an unexpected survival advantage during influenza infection perhaps due to significantly reduced inflammatory mediator induction in the animals." (PMID 30532653, 2018). "In mammals, low expression of TLR3 leads to an unexpected survival advantage, efficient viral replication and decreased lung lesions were confirmed in TLR3-deficient mice after influenza infection." (PMID 24016341, 2013). "In this case, a missense mutation (908T/C) in the TLR3 gene was identified and was shown to be a loss-of-function mutation, suggesting a protective role for TLR3 signaling in severe influenza infection." (PMID 22110538, 2012). "As TLR3/4/7 responses may also contribute to influenza pathogenesis by causing excessive pro-inflammatory cascades, we also investigated the capacity of ssON to limit cytokine production upon TLR3 activation of IAV-infected MoDC." (PMID 31572376, 2019). "Furthermore, TLR3 polymorphisms have been shown to be related to severe cases of influenza infection in humans and mice and its upregulation has been associated with severe pulmonary lesions in the ferret model after IAV infection." (PMID 27825367, 2016). "Moreover, the induction of local pulmonary inflammation such as that caused by TLR3 activation has been found to protect against influenza infection in mice." (PMID 23151015, 2012). "Taken together, the data show that development of an intranasal SARS-CoV-2 vaccine based on recombinant RBD adjuvanted with a TLR3 agonist is feasible, also as a combination vaccine against influenza." (PMID 36944687, 2023). "AR IRF9 deficiency, AR IRF7 deficiency, AD TLR3, and AR IFNAR2 deficiency also underlie influenza pneumonia." (PMID 36976641, 2023). "Specifically, infections with HSV-1, influenza, and, most recently, SARS-Co-V2 have been attributed to pathogenic germline variants in TLR3 pathway genes." (PMID 34199501, 2021). "Genetic variations in TLR3-mediated immune responses can as well explain severe complications manifested in some influenza patients." (PMID 34696494, 2021). "Nonetheless, an antibody against the TLR3 FYW peptide exhibited efficiency in a mouse model of influenza." (PMID 33805888, 2021). "Here, we provide novel data showing that the transcription factor Interferon regulatory factor 5 (IRF5) controls cellular and metabolic responses to influenza infection and TLR3 activation in vivo." (PMID 33423291, 2021). "Mutations in the TLR3 gene predispose to herpes simplex virus 1 (HSV1) encephalitis (HSE), severe influenza pneumonia, and varicella zoster virus (VZV) ophthalmicus." (PMID 32936395, 2020). "TLR3 stimulation during influenza infection resulted in activation of IRF3 and increased type III IFN production." (PMID 32477965, 2020). "Metformin- and glibenclamide-treated DM patients exhibited reduced IFN-α expression upon stimulation with whole- and split-virion influenza vaccines, but only metformin had a TLR3/RIG-I-induced effect upon IFN-α expression." (PMID 32094377, 2020).